IL6 (interleukin 6)
Diseases named in the same sentence as IL6 in open-access papers (continued):
Sharing a sentence is not in itself a finding about the gene and the disease.
breast cancer (continued). "Blocking of IL-6 signalling in breast cancer cells and adipocytes, decreased proliferation, migration and invasion capabilities and altered the expression of genes regulating EMT." (PMID 29891854, 2018). "Various studies have independently shown that growth factors such as TGF-β and IL-6 secreted by stromal cells in the breast cancer microenvironment can influence cancer progression by enhancing migration, invasion and inducing EMT30–32." (PMID 29891854, 2018). "As a result, the pro-inflammatory CAAs exhibit an increased expression of IL-6 and a proliferation-promoting effect on breast cancer cells." (PMID 30200265, 2018). "Together, this data demonstrates that CD11b+/Ly6C+/Ly6G+ BM-MDSCs generated using IL-6 and GM-CSF in vitro, display similar morphological and functional properties to G-MDSCs expanded in the presence of a mammary tumor in vivo." (PMID 29677215, 2018). "IL-6R siRNA treatment, Dia, and 5-Aza treatment lead to reduced proliferative ability in hypoxic breast cancer cells due to inhibition of IL-6/IL-6R or activation of MAO-A." (PMID 29695771, 2018). "The non-cell-autonomous ATR-related enhancement of the migration/invasion abilities of breast cancer cells was mediated in an SDF-1/IL-6-dependent manner." (PMID 30410668, 2018). "After cisplatin treatment, the MSCs not only changed the phosphorylation level of many kinases, but also increased the secretion of IL-6 and IL-8, which increased the chemotherapeutic resistance of breast cancer cells to cisplatin." (PMID 30175384, 2018). "Breast cancer growth and invasion has also been shown to be sensitive to IL-6 through chronic STAT3 activation." (PMID 30487436, 2018). "Western blot of cytoplasmic and nuclear fraction showed an increased expression of pSTAT3 in nuclear fraction of co-cultured cells than in nuclear fraction of control and IL-6-blocked breast cancer cells." (PMID 29891854, 2018). "Our results demonstrated that, of the adipocyte-derived adipokines, IL-6 and leptin were highly expressed after coculture with breast cancer cells." (PMID 30563531, 2018). "Proinflammatory cytokines and chemokines such as IL-1, IL-6, IL-8, and TNFα, and NF-κB family transcription factors are also recognized as important factors in inflammation and breast cancer." (PMID 29315254, 2018). "TGF-β and IL-6 are secreted by adipocytes, hence an understanding of how these factors secreted by adipocytes influence breast cancer migration and invasion is required." (PMID 29891854, 2018). "These pathways are closely related to the regulation of IL-6 and their interactions with IL-6 also affect the characteristics of breast cancer stem cells." (PMID 30175384, 2018). "ZEB1 in the progression of breast cancer controlled the production of IL-6 and IL-8, along with the initiation of EMT." (PMID 30306207, 2018). "In our previous study, we demonstrated that tumor-derived IL-6 positively correlated with MDSC infiltration in situ in human primary breast cancer tissues, which correlated with more aggressive tumor phenotypes and worse clinical outcomes." (PMID 30083161, 2018). "In a longitudinal sample of BCS, elevated IL-6 levels were associated with more cognitive complaints, and in a sample of breast cancer patients, impaired memory function by radiation therapy was suggested to be partially mediated by elevated IL-6." (PMID 30126098, 2018). "Some reports showed that IL-6 is a growth factor involved in breast cancer, lung cancer, hepatocellular carcinoma, gastric cancer, and ovarian cancer." (PMID 29731768, 2018). "The results in both human and mice implied that tumor-derived IL-6 involved in the hyperactivation of the JAK/STAT signaling pathway, which was the main cause of the development of competent e-MDSCs in breast cancer." (PMID 30083161, 2018). "EMT-related gene expression was also reversed after was IL-6 blocked, E-cadherin was upregulated, whiles N-cadherin and MMP9 were downregulated in both breast cancer cells after IL-6 blocking." (PMID 29891854, 2018).
breast cancer (continued). "Interleukin-6 (IL-6), a well-known inflammatory cytokine in the gp130 family, promotes breast cancer metastasis." (PMID 29898744, 2018). "As evidence linking IL-6 to poor outcome and low quality of life in breast cancer patients grows, it has become increasingly important to understand how psychosocial factors of daily life affect the synthesis and function of this versatile cytokine." (PMID 30546293, 2018). "Further studies are therefore needed to better understand the precise role played by adipose tumor microenvironment and by adipokines such as IL-6, leptin and TNFα in breast cancer progression." (PMID 29389973, 2018). "It has previously suggested that IL-6 stimulated the proliferation of breast cancer cells mainly through the activation of STAT3 and cell migration through the activation of the RAS/MEK/ERK and PI3K/AKT signaling pathways." (PMID 29707128, 2018). "We show here that RA activates the pro-invasive axis Src-YAP-Interleukin 6 (Src-YAP-IL6) in triple negative MDA-MB-231 breast cancer cells, yielding to increased invasion of these cells." (PMID 29728589, 2018). "In contrast, HIF-1α expression was sharply reduced in transfected IL-6 siRNA or Dia exposed breast cancer cells in hypoxic environment." (PMID 29695771, 2018). "Our study represents, to our knowledge, the first trial to examine the impact of preadipocytes and IL-6 in the use of DCIS cells as a breast cancer model of early stage." (PMID 30134951, 2018). "To better understand the effect of paracrine IL-6 signalling in adipocyte-breast cancer interaction we determined the proliferation, migration and invasion characteristics of breast cancer cells in co-culture system after IL-6 signalling was blocked." (PMID 29891854, 2018). "Using a stable STAT3 reporter breast cancer cells, we observed the activity of STAT3 decreased after IL-6 signal was blocked in breast cancer cells." (PMID 29891854, 2018). "Local IL-6 paracrine loop act as exogenous IL-6 rich niche for chemo-sensitive breast cancer cells, leading to de novo acquired drug resistance." (PMID 30175384, 2018). "MSCs migrate towards breast cancer cells via hypoxia-induced interleukin 6 (IL6) secretion and towards primary breast tumors via the hypoxia-inducible factor alpha (HIFα)-dependent secretion of CXCL16." (PMID 29642534, 2018). "It is very conceivable that one of the driving forces in increasing cell migration and invasion here are pro-inflammatory cytokines, like IL-6 and IL-8, secreted from mature adipocytes, which are known to play a role in breast cancer progression." (PMID 29930291, 2018). "Taken together, these finding indicate that human adipocytes activated IL-6/STAT3 signalling in breast cancer cells." (PMID 29891854, 2018). "Local TAFs in breast cancers act as a paracrine source of the elevated IL-6, driving STAT3 activation and ERα-positive tumor cell proliferation both in vitro and in vivo." (PMID 29463044, 2018). "But the direct effect of IL-6 on breast cancer cell is not fully understood, and recent studies were paradoxical on IL-6 dependent effect on the proliferation and invasion of breast cancer cells." (PMID 30083161, 2018). "In turn, breast cancer cells co-cultured with stroma induce secretion of IL-6 and IL-8 by the stroma, creating a positive feedback loop." (PMID 30119678, 2018). "Recent studies have demonstrated that the IL-6 plays an important role in tumor progression and metastasis and is expressed in approximately 50% of breast cancers." (PMID 30083161, 2018). "Analogously, the combination of anti-VEGFA and anti-IL-6 blocking antibodies was more efficient in inhibiting the spontaneous migration of breast cancer cells as compared with a single antibody." (PMID 29707128, 2018). "IL-6, a proinflammatory cytokine, has been shown to enhance ERα-positive breast cancer cell growth and invasion." (PMID 29463044, 2018).
breast cancer (continued). "Co-culture of breast cancer cells with fibroblasts also led to an increase of murine IL-6 from fibroblasts, but to a much lesser extent." (PMID 29930291, 2018). "IL-6 neutralization significantly blocked the seeding and metastatic growth of breast cancer cells in the bone." (PMID 30013512, 2018). "Based on our qRT-PCR results, we next detected levels of secreted IL-6 and leptin in the medium of 3 T3-L1 preadipocytes, adipocytes and adipocytes cocultured with breast cancer cells." (PMID 30563531, 2018). "The initial upregulation of EMT-TF TWIST in co-cultured breast cancer cells was also reversed after IL-6 signalling was blocked in both breast cancer cells." (PMID 29891854, 2018). "This was of special interest, since interleukins, such as IL-8 and IL-6, are considered to be metastatic factors in breast cancer progression." (PMID 29930291, 2018). "Cyclooxygenase-2 (COX-2), tumor necrosis factor-alpha (TNF-α), vascular endothelial growth factor (VEGF) and IL-6 are all inflammation mediators that play critical roles in metastasis and progression of breast cancer." (PMID 30155724, 2018). "Both the CC chemokine ligand 5 (CCL5/RANTES) and interleukin-6 (IL-6), released by mesenchymal stem cells (MSCs) as well as by neoplastic cells, promote breast cancer cell progression through autocrine and paracrine mechanisms." (PMID 29707128, 2018). "In preclinical studies, IL-6 has been demonstrated to promote breast cancer cell migration in cooperation with EGFR signaling, through an autocrine loop involving EGF family ligands that contribute with IL-6 in inducing ERK activation." (PMID 29707128, 2018). "Co-culture experiments revealed that adipocytes co-cultured with breast cancer cells overexpress inflammatory cytokines such as IL-6, TNFα, and MMPs, which promote tumor cell invasion." (PMID 29805773, 2018). "We studied a co-relation among MAO-A and IL-6/IL-6R and tumour angiogenesis/invasion in hypoxic environment in breast cancer model." (PMID 29695771, 2018). "In conclusion, this study validated the rational for targeting IL-6/IL-6R-MAO-A axis for development of novel therapeutic for breast cancer management." (PMID 29695771, 2018). "For example, in breast cancer metastasis to the bone, osteoblasts secrete the inflammatory cytokine interleukin 6 (IL6) induced by Notch activation contributes to metastatic outgrowth." (PMID 29506506, 2018). "When either co-cultured with MDA-MB-231 metastatic breast cancer cells or treated with their conditioned media, we found that osteoblasts increased their production of the inflammatory cytokines IL-6, IL-8, and MCP-1." (PMID 29867053, 2018). "Recently, it was revealed that proinflammatory cytokines in serum, such as IL-6, IL-8, and TNF-α, are associated with clinical stage and lymph node metastasis in breast cancer patients." (PMID 30034291, 2018). "The crosstalk between Notch pathway and IL-6 in breast cancer cells seems to be mediated also by NF-κB." (PMID 30154786, 2018). "In breast cancers, IL-6-expressing 4T1 mammary tumor-bearing mice were reported to dramatically enhance the recruitment of CD11b+Gr-1+ MDSCs in the spleen, primary tumor mass, and metastasizing organs when compared with low IL-6-expressing EMT6 mice." (PMID 30083161, 2018). "To determine if adipocytes induced proliferation, migration and invasion in breast cancer cells occur by a similar mechanism, we compared the expression of IL-6, STAT3 and phosphorylated STAT3 (Y705) in breast cancer cells co-cultured with adipocytes." (PMID 29891854, 2018). "The effects of RANTES and IL-6 co-expression on the phenotype of breast cancer cells were more marked in MCF-7 cells, a poorly aggressive ER positive luminal cell line, as compared with the highly aggressive basal MDA-MB-231 cell line." (PMID 29707128, 2018). "Blocking IL-6 resulted in E-cadherin upregulation in both breast cancer cells, while the expression TWIST and N-cadherin was downregulated." (PMID 29891854, 2018).
breast cancer (continued). "The increased wound closure rate in co-cultured breast cancer cells was decreased significantly (p < 0.05) after blocking IL-6 signalling." (PMID 29891854, 2018). "For example, CSCs in breast cancer produce cytokines such as IL-6 to attract the MSCs, which then produce CXCL7." (PMID 29506506, 2018). "Addition of breast cancer-derived exosomes to macrophages results in the activation of the IL-6 response pathway, including phosphorylation of the key downstream transcription factor STAT3." (PMID 29867925, 2018). "Liu Suling 22, 23 reported that breast cancer stem cells can secrete IL‐6, which can up‐regulate CXCL7 production by mesenchymal cell." (PMID 29356357, 2018). "Dose dependent Dia (An IL-6/IL-6R signalling inhibitor) treatment was performed in normoxic, as well as hypoxic breast cancer cells." (PMID 29695771, 2018). "Collectively, this work demonstrates that breast cancer-derived exosomes are capable of inducing IL-6 secretion and a pro-survival phenotype in macrophages, partially via gp130/STAT3 signaling." (PMID 29867925, 2018). "In this study, we constructed IL-6-knockdown breast cancer mice models to explore the molecular events involved in the IL-6-mediated effects on MDSC development." (PMID 30083161, 2018). "The activation of Notch pathway induces the expression of IL-6 in malignant cells of different tumors, i.e., in colon cancer, stimulates tumor cell proliferation, and in luminal breast cancer, it promotes self-renewal and drug resistance." (PMID 30154786, 2018). "IL-6R Ab and a specific STAT3 antagonist inhibited the growth and metastasis of IL-6+ mammary cancer in vivo and dramatically reduced the accumulation of e-MDSCs." (PMID 30083161, 2018). "IL-6 levels were increased in adipocytes cultured with both breast cancer cells, whereas TGF-β levels was increased only in adipocytes cultured with MDA-MB-468 cells but not with MCF-7 cells." (PMID 29891854, 2018). "In summary, we propose that IL-6 is an important mediator involved in the cross-talk between preadipocytes and breast DCIS cells, which is associated with early stage breast cancer progression." (PMID 30134951, 2018). "In fact, both VEGFA and IL-6 were able to significantly increase the ability to migrate of different breast cancer cell lines, with the combination of the two factors showing a greater effect as compared to treatment with a single protein." (PMID 29707128, 2018). "Activation of Src should be relevant for activation of YAP and upregulation of IL-6 in MDA-MB-231 breast cancer cells since inhibition of Src by PP2 or silencing Src expression in these cells decreases PY-YAP and downregulates IL-6 expression." (PMID 29728589, 2018). "The complex pathophysiology that exists between adipose tissue, inflammation and breast cancer involves inflammatory mediators (i.e., IL-6 and TNF-α) that enhances tumor progression and survival." (PMID 30619088, 2018). "Similar effect was also observed due to IL-6/IL-6R inhibition by Dia treatment in hypoxic breast cancer cells." (PMID 29695771, 2018). "In our work here, we demonstrate that co-culture with differentiated adipocytes not only induces IL-6 and IL-8 gene expression and production within TN breast cancer cells, but also increases murine IL-6 production of the adipocytes." (PMID 29930291, 2018). "It has been shown that IL6_HUMAN is involved in the progression of several cancers, extremely responsible for leukemia, breast cancer and lymphoma." (PMID 29593668, 2018). "The increased iron uptake reinforces the IL-6 paracrine loop between TAMs and breast cancer cells, leading to intensive de novo acquired chemo-resistance." (PMID 30591630, 2018). "Taken together, these data indicate that blocking paracrine IL-6 signalling between breast cancer and adipocytes significantly inhibit the proliferation, migration and invasive capabilities of MDA-MB-468 and MCF-7 breast cancer cells." (PMID 29891854, 2018).
breast cancer (continued). "Adipocyte-stimulated migration of breast cancer cells toward the lungs was impeded by treatment with a murine IL-6 blocking antibody or depletion of OBR." (PMID 30563531, 2018). "To identify paracrine regulator of EMT in adipocyte and breast cancer cell interaction, we compared mRNA expression of TGF-β and IL-6 (two prominent inducers of EMT) in breast cancer cells." (PMID 29891854, 2018). "Together these results indicate that breast cancer cells provoke increased IL-6 secretion from adipocytes which probably feeds into the pro-inflammatory signaling loop of the breast cancer cells." (PMID 29930291, 2018). "The initial decrease in E-cadherin expression in breast cancer cells co-cultured with adipocytes was reversed after IL-6 signalling was blocked in both MDA-MB-468 and MCF-7." (PMID 29891854, 2018). "In conclusion, given the critical role of BCSCs in conferring chemoresistance, enhancement of IL-6 to BCSCs population reveals the clew of that it can promote the resistance of breast cancer cells to chemotherapeutic drugs." (PMID 30175384, 2018). "Elevated levels of serum IL-6 are a biomarker of poor prognosis in most malignancies, including breast cancer." (PMID 29707128, 2018). "Breast cancer stem cells secrete IL-6, recruit mesenchymal stem cells, and induce their production of CXCL7 cytokines to support the cancer stem cell phenotype, and IL-6 can also induce differentiated tumor cells to transform into tumor stem cell phenotypes." (PMID 30344611, 2018). "It does so, in part, by regulating production of GM-CSF, IL1α, IL-6, and TNFα by breast cancer cells." (PMID 29593211, 2018). "Evidence suggests that RANTES and IL-6 play a relevant role in the pathogenesis and progression of breast cancer." (PMID 29707128, 2018). "In this respect, we have previously demonstrated that VEGFA and IL-6 cooperate in inducing the migration of breast cancer cells." (PMID 29707128, 2018). "Suppression of MAO-A by IL-6/IL-6R activation promotes tumour angiogenesis and invasion in hypoxic breast cancer environment." (PMID 29695771, 2018). "Leptin and IL-6 signaling in breast cancer cells adjacent to adipocytes upregulate multiple pathways including Notch promoting a stem-like phenotype as well as epithelial-mesenchymal transition." (PMID 30515368, 2018). "As COX-2, TNF-α, VEGF-A and IL-6 are pro-metastatic and B(a)P upregulates these mediators, it is possible that B(a)P can increase breast cancer cell metastasis." (PMID 30155724, 2018). "IL-6, secreted from stromal cells including tumor-associated macrophages and T cells, can promote EMT in breast cancer cells, with the induction of vimentin, N-cadherin, Snail, and Twist." (PMID 30487436, 2018). "Although the role of these factors has been well established, our data demonstrate for the first time that RANTES and IL-6 cooperate in promoting the aggressiveness of breast cancer cells." (PMID 29707128, 2018). "Previous studies showed that IL-6 from adipose stromal cells (ASCs) promoted the migration and invasion of ER (-) mammary cancer." (PMID 30013512, 2018). "Our findings are also in line with recent results which show that SHP2 is required for epithelial-to-mesenchymal transition induced by IL-6 in breast cancer cells." (PMID 30108215, 2018). "The interplay between IL-6 and Notch has been studied in depth in multiple myeloma and breast cancer." (PMID 30154786, 2018). "Expression of IL-6 increased while leptin expression decreased when adipocytes were cocultured with MDA-MB-231 breast cancer cells." (PMID 30563531, 2018). "We defined a subset of early-stage MDSCs (e-MDSCs) with the phenotype of CD11b+Gr-1−F4/80−MHCII− in IL-6 high-expressing 4T1 mice mammary carcinoma models, which were the precursors of CD11b+Gr-1+ conventional MDSCs." (PMID 30083161, 2018). "In vitro and in vivo studies have shown that CAFs derived from breast cancer induced tamoxifen resistance through decreasing estrogen receptor-α (ER-α) levels and IL-6 secretion." (PMID 28754000, 2017).